RNU6-813P (RNA, U6 small nuclear 813, pseudogene)
Gene: Small nuclear RNA gene on chromosome 6 (151,615,773 to 151,615,879, reverse strand). Ensembl gene ENSG00000207422.
Homologues: Orthologues: chimpanzee U6 (100% identical), macaque U6 (91% identical), dog U6 (70% identical), pig U6 (69% identical), dog U6 (65% identical). Paralogues in human: RNU6-41P (82% identical), RNU6-259P (81% identical), RNU6-45P (81% identical), RNU6-891P (81% identical), RNU6-1042P (80% identical), RNU6-10P (80% identical), RNU6-1145P (80% identical), RNU6-1201P (80% identical), RNU6-12P (80% identical), RNU6-13P (80% identical), RNU6-166P (80% identical), RNU6-25P (80% identical), and 1291 more.